IFIH1 (interferon induced with helicase C domain 1)
Diseases named in the same sentence as IFIH1 in open-access papers (continued):
Sharing a sentence is not in itself a finding about the gene and the disease.
dermatomyositis (306 papers, 2011 to 2026). Dermatomyositis (DM) is a type of idiopathic inflammatory myopathy characterized by evocative skin lesions and symmetrical proximal muscle weakness. "MDA5, encoded by the IFIH1 gene, is reported to be positive in approximately 11–60% of dermatomyositis cases, with a positivity rate of 6-12% in children." (PMID 37974162, 2023). "Specific IFIH1 variants results in MDA5+ overactivation, causing autoimmune diseases like Aicardi-Goutières syndrome (AGS), Singleton-Meyer syndrome (SMS), dermatomyositis and type-1 diabetes." (PMID 40963624, 2025). "Dermatomyositis patients with interstitial lung disease often harbor autoantibodies against an intracellular RNA sensor protein, MDA-5 (IFIH1), but the mechanism behind the association of autoantibodies with lung disease is not known." (PMID 33763057, 2021). "It is interesting to note that polymorphisms in IFIH1 have been reported in patients with inflammatory myopathies and anti-MDA5 antibodies are seen in some patients with amyopathic dermatomyositis." (PMID 30459768, 2018). "For example, recognition of a 140 kDa autoantigen in dermatomyositis preceded its definitive identification as IFIH1 by 4 years." (PMID 21629782, 2011). "In addition, evidence supports the involvement of IFIH1 SNPs in inflammatory diseases such as type 1 diabetes, inflammatory bowel disease, and dermatomyositis." (PMID 36425068, 2022). "Enhanced skin expression of IFIH1 (MDA5) in dermatomyositis and related autoimmune diseases." (PMID 27344170, 2016). "Although an increase in IFIH1 autoantibodies (anti-MDA5 antibodies) have not been reported in T1D, it may be of interest to assess in future studies if Ifih1R/R impacts development of these autoantibodies, which are deleterious in patients with dermatomyositis." (PMID 38487540, 2024).
interstitial lung disease (235 papers, 2011 to 2026). A diverse group of lung diseases that affect the lung parenchyma. "Its encoding gene, IFIH1, is highly upregulated in both COVID-19 infection and autoimmune interstitial lung disease (ILD)." (PMID 39872589, 2024). "Individuals with autoantibodies targeting the cytoplasmic nucleic acid sensor MDA5 (also called interferon induced with helicase C domain 1, IFIH1) can present with rapidly progressive interstitial lung disease associated with high mortality." (PMID 33772100, 2021). "For instance, elevated CXCL10 expression was observed in patients with interstitial lung disease (ILD), leukopenia, and anemia; JAK2 expression differed in rheumatoid arthritis comorbidity; IFIH1 expression also showed differences in those with Raynaud's phenomenon and ILD." (PMID 41929488, 2026).
myositis (158 papers, 2012 to 2026). "For example, autoantibodies against the intracellular autoantigen MDA5, encoded by the IFIH1 gene, are found in myositis-associated lung disease, but mutations in the IFIH1 gene cause an unrelated disease characterized by a spectrum of neuro-immunological features." (PMID 33763057, 2021).
autoimmune disease (101 papers, 2009 to 2025). A disorder resulting from loss of function or tissue destruction of an organ or multiple organs, arising from humoral or cellular immune responses of the individual to their own tissue constituents. "Approximately 30 distinct gain‐of‐function mutations in IFIH1, the gene that encodes MDA5, have been linked to autoimmune diseases in humans, such as AGS, Singleton‐Merten syndrome (SMS), SLE, DM, and type 1 diabetes." (PMID 40525588, 2025). "A meta-analysis indicated that the IFIH1 rs1990760 T allele is significantly associated with susceptibility to autoimmune diseases, including systemic lupus erythematosus, multiple sclerosis, and rheumatoid arthritis." (PMID 39595128, 2024). "Subsequently, we performed a meta-analysis on the association of the SNP rs1990760, rs3747517, and rs10930046 in the IFIH1 gene with susceptibility to autoimmune diseases." (PMID 37426657, 2023). "Mutations in IFIH1 are also associated with other autoimmune diseases, including multiple sclerosis (MS), systemic lupus erythematosus (SLE), and rheumatoid arthritis (RA)." (PMID 36512407, 2023). "The results displayed significant associations between IFIH1 rs1990760 A allele and rs3747517 C allele and autoimmune diseases risk (OR=1.09, 95% CI: 1.01~1.17; OR=1.24, 95% CI: 1.15~1.25, respectively)." (PMID 37426657, 2023). "Previous studies have shown that the IFIH1 rs1990760 polymorphism is associated with a variety of autoimmune diseases, including type 1 diabetes, systemic lupus erythematosus, multiple scleral hyperplasia and rheumatoid arthritis." (PMID 35041675, 2022). "The rs1990760/IFIH1 (C/T) polymorphism results in a change of an alanine to threonine (Ala946Tre) in MDA5, which predispose carriers to a number of autoimmune diseases." (PMID 36672770, 2022). "The IFIH1 gene locus has been recently defined as a candidate for susceptibility to autoimmune diseases like vitiligo, T1D and GD." (PMID 32974248, 2020). "Here we demonstrated the contribution of polymorphic variants of genes encoding IL2RA, CTLA-4, and IFIH1 to autoimmune diseases predisposition." (PMID 32974248, 2020). "One of these gene loci IFIH1, previously proven to be related with several autoimmune diseases, was recently defined as a candidate for susceptibility to GV." (PMID 30761886, 2019). "Accordingly, we aimed to investigate the association of IFIH1 gene polymorphisms with susceptibility of GV and the autoimmune diseases accompanying GV." (PMID 30761886, 2019). "IFIH1 has been reported to be associated with several autoimmune diseases such as T1D, Graves’ disease, multiple sclerosis, psoriasis, and possibly lupus (u28ef,u28f2); it has also been recently defined as a candidate for susceptibility to GV (u28f3)." (PMID 30761886, 2019). "The objectives of this study were to assess the association of IFIH1 gene, rs2111485, and rs1990760 single-nucleotide polymorphisms (SNP) with susceptibility to GV and the autoimmune diseases accompanying GV." (PMID 30761886, 2019). "Future studies will need to investigate the risk:benefit ratio of modulating MDA5 (encoded by IFIH1) for asthma relative to autoimmune diseases." (PMID 30327483, 2018). "Several studies have shown that the autoimmune-disease-associated allele of IFIH1 (rs1990760 T, 946 T) is likely to be a gain-of-function variation." (PMID 29930297, 2018). "Previous GWAS on IFIH1 identified the association between few SNPs in this gene with the risk of various autoimmune diseases including type 1 diabetes (T1DM), multiple sclerosis, psoriasis, selective IgA deficiency, dilated cardiomyopathy and SLE11,12." (PMID 29930297, 2018). "The results of meta-analysis revealed significant association between the IFIH1 rs1990760 polymorphism and autoimmune diseases including T1DM and SLE22." (PMID 29930297, 2018). "First, IFIH1 has been linked to a number of autoimmune diseases, including AGS, SLE, psoriasis, and diabetes." (PMID 28955379, 2017).
autoimmune disease (continued). "Type 1 interferonopathy (exposure to type 1 interferon too much, for too long or at the wrong time) is reported to be linked with many inflammatory or autoimmune diseases including IFIH1-mutation associated AGS and SLE." (PMID 28955379, 2017). "A common polymorphism in IFIH1 (rs1990760, A946T) confers increased risk for autoimmune disease, including type 1-diabetes (T1D)." (PMID 28000722, 2016). "So far, numerous of case-control studies had been conducted to assess the associations of the IFIH1 rs1990760 and rs3747517 polymorphisms with many kinds of autoimmune diseases." (PMID 25337792, 2014). "The SNPs (rs1990760 and rs3747517) in IFIH1 gene chose in our study were those with the strongest associations with other autoimmune disease in the Chinese Han population." (PMID 25337792, 2014). "An autoimmune disease risk variant for MDA5 (IFIH1), which binds dsRNA and results in increased sensitivity to IFN-α has been described." (PMID 23826184, 2013). "The association between IFIH1 rs1990760 polymorphism and T1D was not only confirmed by other authors but also reported in other autoimmune diseases." (PMID 19961590, 2009). "Variants of IFIH1 could alter basal or pathogen-induced cell signaling cascades that influence immune cell populations and susceptibility to autoimmune diseases such as T1D." (PMID 38487540, 2024). "The SNPs of IFIH1 could cause the abnormal activation of antiviral defenses signaling leading to the autoimmune disease development." (PMID 32974248, 2020). "To examine whether this may be a chance finding, we examined whether the common IFIH1 missense variant rs1990760, previously identified as associated with autoimmune disorders, also associated with risk of coronary artery disease." (PMID 29691411, 2018). "This is contrasted to heterozygous gain-of-function IFIH1 mutations in autoimmune diseases." (PMID 29018476, 2017). "We hypothesized that the Treg-specific constitutive activation of MDA5, by expressing the gain-of function mutant G821S of the Ifih1 gene (referred to as MDA5 G821S), would result in Treg population loss and the onset of autoimmune diseases, similar to that observed in Foxp3ΔAdar1 mice." (PMID 38427731, 2024). "IFIH1 plays a role in the innate immune system by recognizing viruses and initiating antiviral responses; however, its functional upregulation may modestly increase the risk of autoimmune diseases." (PMID 39595128, 2024). "Furthermore, in the meta-analysis Cen and colleagues analyzed 19 studies and revealed that the IFIH1 rs1990760 T allele influences susceptibility to T1D and other autoimmune diseases like systemic lupus erythematosus, multiple sclerosis and rheumatoid arthritis." (PMID 32974248, 2020). "Indeed, some reports indicate that IFIH1 mutations are related to various autoimmune diseases such as diabetes mellitus Type I, systemic lupus erythematosus, Graves’ disease, multiple sclerosis, rheumatoid arthritis, Hashimoto’s thyroiditis, and autoimmune Addison’s disease." (PMID 31427910, 2019). "Interferon induced with helicase C domain 1 (IFIH1) single-nucleotide polymorphisms (SNP) rs1990760, rs3747517, and rs10930046 have been shown to be closely related to the risk of autoimmune diseases." (PMID 37426657, 2023). "Interferon-induced helicase C domain 1 (IFIH1), encoding MDA5, is associated with autoimmune diseases." (PMID 33879674, 2021). "As a cytoplasmic sensor of viral RNA, IFIH1, is able to activate type 1 interferon (IFN) and multiple proinflammatory cytokines and is implicated in inflammatory or autoimmune diseases." (PMID 34671386, 2021). "Polymorphisms in the Interferon Induced with Helicase C Domain 1 (IFIH1) gene, a gene encoding a cytoplasmic viral RNA receptor that activates type-I IFN signaling, are considered risk factors for various autoimmune diseases, including classical psoriasis." (PMID 33114187, 2020).
autoimmune disease (continued). "A shared haplotype of two common IFIH1 variants (rs1990760, A946T, and rs3747517 H843R) cause constitutively active IFN signaling and pre-disposition to autoimmune diseases." (PMID 31866997, 2019). "As such, the results of both our investigation and the Funabiki study support the role of IFIH1 in autoimmune disease through its potential to influence dysregulation of inflammatory pathways." (PMID 28234905, 2017). "Autoimmune diseases like AGS are clearly linked to nucleic acid metabolism since mutations in TREX1, RNASEH2A-2C, SAMHD1, ADAR1, or IFIH1 predispose individuals to disease (12, 48, –, 51)." (PMID 28679751, 2017). "The link between the strength of their expression and the rs199760 polymorphism in IFIH1 warrants further investigations on the role of type III IFNs in infectious and autoimmune diseases." (PMID 28000722, 2016). "IFIH1 is the gene that encodes MDA5, and a common coding-change polymorphism in the IFIH1 gene has been associated with risk of SLE and other autoimmune diseases in humans." (PMID 25505487, 2014). "The IFIH1 gene, which encodes the RNA sensor MDA5, is a risk factor in several autoimmune diseases, including SLE." (PMID 25147296, 2014). "The mechanisms by which the IFIH1 polymorphisms modify the risk of T1D and other autoimmune diseases are presently unknown, but most works agree that the minor alleles (protective from T1D) are associated with diminished transcription or reduced function of the IFIH1." (PMID 23144876, 2012). "IFIH1 transcripts were found to be expressed in lymphoid and other tissues, suggesting a role in autoimmune diseases." (PMID 19961590, 2009). "In addition, a relationship has been identified between IFIH1 and various autoimmune diseases, including SLE and type 1 diabetes mellitus." (PMID 39119144, 2024). "Therefore, it is important to define how genetic mutations in IFIH1 contribute to MDA5 function, since this knowledge would apply not only to T1D but also to other autoimmune diseases." (PMID 36512407, 2023). "The IFIH1 gene encodes melanoma differentiation-associated gene 5 (MDA5) and has been associated with Aicardi-Goutières syndrome (AGS), Singleton-Merten syndrome (SMS), and other autoimmune diseases." (PMID 34054923, 2021). "According to the literature genes encoding IL2RA (alpha subunit of Interleukin 2 receptor), IFIH1 (Interferon induced with helicase C domain 1) and CTLA-4 (cytotoxic T cell antigen 4) might be associated with autoimmune diseases pathogenesis." (PMID 32974248, 2020). "Genetic variations in Ifih1 in humans are also associated with increased type I IFN signaling and an increased risk for the development of a number of autoimmune disorders, including Aicardi-Goutieres syndrome, systemic lupus erythematosus, and type I diabetes." (PMID 29723194, 2018). "We intend to examine the genetic contribution of TNFAIP3, IFIH1, and IRF5 to PM/DM based upon the postulated roles of each of these genes' products in innate and cell-mediated immunity in PM/DM and their described associations with autoimmune diseases." (PMID 25337792, 2014). "While low-activity variants could predispose one to infection, IFIH1 variants that result in a MDA5 gain of function might result in the overactivation of inflammatory pathways and the increased risk of inflammatory and autoimmune diseases." (PMID 37834254, 2023). "Current publications showed association between autoimmune diseases and chromosome 10p15 region for IL2RA (interleukin 2 receptor-α), chromosome 2q33 region for CTLA-4 (cytotoxic T-lymphocyte antigen-4) and chromosome 2q24 region for IFIH1 (interferon induced with helicase C domain 1)." (PMID 32974248, 2020). "In this study, we identified pLOF variants that protect against obesity (GPR151), asthma (GSDMB, IL33), autoimmune disorders (IFIH1), and coronary artery disease (PDE3B), prioritizing genes and pathways for which pharmacologic attempts to mimic these protective mutations might ameliorate disease." (PMID 29691411, 2018).
autoimmune disease (continued). "Genome-wide association (GWA) studies have shown that supposedly activating IFIH1 variants – analogous to fully penetrant gain-of-function mutations underlying the dominant Mendelian diseases AGS and SMS – are implicated in the pathogenesis of autoimmune disorders such as type 1 diabetes and SLE." (PMID 29018476, 2017). "Rare loss-of-function variations in IFIH1 have been discovered in the IFIH1 gene, and interestingly these loss-of-function variants appear to be protective against autoimmune disease, further supporting the idea that increased function of IFIH1/MDA5 is associated with risk of autoimmune disease." (PMID 25505487, 2014). "Similar to other studies, that investigated IFIH1 rs1990760 polymorphism in diverse autoimmune disease we could not find a association between IFIH1 rs1990760 polymorphism and our case-control study population." (PMID 19961590, 2009). "Non-HLA genes associated with sIgAD include IFIH1 and CLEC16A, both linked to autoimmune diseases like type 1 diabetes (T1D) and multiple sclerosis." (PMID 39712011, 2024).
COVID-19 (75 papers, 2020 to 2025). A disease caused by infection with severe acute respiratory syndrome coronavirus 2. "Recently, IFIH1 variants have also been associated with an increased risk for severe SARS-CoV-2 (COVID-19)." (PMID 37834254, 2023). "As steroids are now the standard of care for severe COVID-19, this sample size cannot be increased outside a hypothetical clinical trial focused of personalized steroid therapy according to IFIH1 rs1990760 variants." (PMID 35060899, 2022). "COVID-19 patients with the IFIH1 rs1990760 TT variant show an attenuated inflammatory response and better outcomes." (PMID 35060899, 2022). "We hypothesized that IFIH1 rs199076 variants would modulate host response and outcome after severe COVID-19." (PMID 35060899, 2022). "We hypothesized that, once infection is established, the inflammatory response in severe COVID-19 patients could be conditioned by IFIH1 variants." (PMID 35060899, 2022). "We reported an association between the T/T genotype of the rs1990760/IFIH1 polymorphism and risk of ICU admission and death in females with COVID-19." (PMID 36672770, 2022). "Our study shows that the rs1799752/ACE1, rs1990760/IFIH1, rs2236757/IFNAR2, rs12329760/TMRPSS2, and rs2304256/TYK2 polymorphisms are genetic risk factors for severe forms of COVID-19 and increased mortality." (PMID 36672770, 2022). "IFIH1 was reported to participate in SARS-CoV-2 sensing and was associated with proinflammatory cytokine overproduction in COVID-19." (PMID 35625619, 2022). "We found that polymorphisms in TMPRSS2, ACE1, IFNAR2, and IFIH1 genes are associated with worse clinical outcomes (ICU admission) and increased mortality in patients with COVID-19, and this is influenced by sex and ethnicity." (PMID 36672770, 2022). "Subsequent studies on peripheral blood mononuclear cells (PBMCs) from acute and convalescent COVID-19 subjects showed that the induction of IFIH1 positively correlated with increased type 1 IFN activity, IFN stimulated gene 15 positive (ISG15+) CD8+ cytotoxic T cell signature, and IFN response, i." (PMID 39439977, 2024). "In addition, IPIN analysis from COVID-19 patient lung tissue revealed that IFIH1, DDX58, ISG15, OASL, and XAF1 were hub genes in the network." (PMID 35625619, 2022). "2D cultures of lung cells and exosome vesicles from COVID-19 patients confirmed IFIH1 and gene signatures of AT2 cytopathies and autoimmune ILD, linking the exposure to SARS-CoV-2 to IFIH1 induction." (PMID 39439977, 2024). "In whole blood study, seven autoantigens were upregulated in blood of severe COVID-19 patients (MPO, PRTN3, PADI4, IFIH1, TRIM21, PTPRN2, and TSHR), while four autoantigens (MPO, PRTN3, IFIH1, and PADI4) were increased in blood of mild patients." (PMID 34276672, 2021). "In conclusion, this study shows an association of rs1799752/ACE1, rs1990760/IFIH1, rs2236757/IFNAR2, rs12329760/TMPRSS2, and rs2304256/TYK2 polymorphisms with worse COVID-19 outcomes, especially among female and non-white patients." (PMID 36672770, 2022). "In comparison to the COVID-19(-) PU controls, genes highly expressed in the TV group fell into categories that included neutrophil dysfunction (CD274, PADI2), inhibition of B and T cell responses (CD22, IRF4, ORAI1), and upregulation of pro-inflammatory response pathways (CARD8, MAPK7, IRF7, IFIH1)." (PMID 37026002, 2023).